NELL1 (neural EGFL like 1)
Diseases named in the same sentence as NELL1 in open-access papers (continued):
Sharing a sentence is not in itself a finding about the gene and the disease.
osteonecrosis (2 papers, 2021 to 2024). A none disease characterized by death of bone tissue due to a lack of blood supply. "We aimed to identify the pro-angiogenic and osteogenic efficacy of adipose tissue-derived (AD) pericytes combined with Nel-like protein-1 (NELL-1) to investigate the therapeutic effects on osteonecrosis." (PMID 34571892, 2021). "Furthermore, the pro-angiogenic efficacy of adipose tissue-derived PCs on tube formation and cell migration was enhanced by Nel-like protein-1 (NELL-1), and promoted bone formation in an osteonecrosis mouse model." (PMID 38275607, 2024). "Thus, combinatorial therapy using AD pericytes and NELL-1 may have potential as a novel treatment for osteonecrosis." (PMID 34571892, 2021). "Thus, combination therapy using AD pericytes and NELL-1 may have potential as a novel treatment for osteonecrosis." (PMID 34571892, 2021).
periodontitis (2 papers, 2023 to 2024). An acute or chronic inflammatory process that affects the tissues that surround and support the teeth. "In addition, the same study suggested that the development of NELL1- and BMP9-related drugs would be promising for the treatment of periodontitis-induced alveolar bone loss." (PMID 37724115, 2023).
rhabdomyosarcoma (2 papers, 2017 to 2022). A rare aggressive malignant mesenchymal neoplasm arising from skeletal muscle. "NELL1 had been identified in previous microarray and microscopy studies, which suggested that it is overexpressed on the surface of target rhabdomyosarcoma cells." (PMID 35447734, 2022). "NELL1 upregulation has been linked with metastasis and negative prognosis in rhabdomyosarcoma (RMS)." (PMID 35447734, 2022). "Our results showed that DNA methylation regulates NELL1 expression in rhabdomyosarcoma." (PMID 28380437, 2017).
sarcoma (2 papers, 2022 to 2023). A usually aggressive malignant neoplasm of the soft tissue or bone. "Indeed, we recently observed that the secreted protein NELL-1 regulates osteosarcomagenesis and OS disease progression, associated with alteration in the sarcoma matrisome and FAK/Src signaling activation." (PMID 36599925, 2023). "NELL1 modulates the sarcoma matrisome and cell-ECM interactions to promote sarcomagenesis and disease progression." (PMID 36599925, 2023). "CNTNAP4 knockout (KO) in OS tumor cells largely phenocopied the effects of NELL-1 KO, including reductions in sarcoma cell attachment, migration, and invasion." (PMID 36599925, 2023). "In summary, our findings demonstrate the biological importance of NELL-1/CNTNAP4 signaling axis in disease progression of human sarcomas and suggest that targeting the NELL-1/CNTNAP4 signaling pathway represents a strategy with potential therapeutic benefit in sarcoma patients." (PMID 36599925, 2023). "Therefore, future studies investigating the role of NELL-1/CNTNAP4 function in sarcoma progression will likely require prospective data collection on single tumor types, including bone-associated sarcomas." (PMID 36599925, 2023). "Thus far, significant similarities had been observed between CNTNAP4 KO sarcoma cells and those effects we recently reported in NELL1 KO cells." (PMID 36599925, 2023). "Moreover, it was discovered that high expression levels of NELL1 are normally linked with negative outcomes in some types of sarcomas." (PMID 35447734, 2022). "Second, it is clear, as alluded to, that both NELL-1 and CNTNAP4 have several binding partners that may play partially redundant roles in sarcoma disease progression." (PMID 36599925, 2023). "This molecular data has shown that NELL-1 is a high-affinity ligand for CNTNAP4 and implies that autocrine NELL-1/CNTNAP4 signaling within sarcoma cells could be a biologically relevant axis that regulates OS disease progression." (PMID 36599925, 2023). "This suggests that NELL-1 exerts at least some effects independent of Cntnap4 and that NELL-1 could have more diverse effects outside of Cntnap4-MAPK-FAK signaling in sarcoma biology." (PMID 36599925, 2023).
schizophrenia (2 papers, 2017 to 2024). A major psychotic disorder characterized by abnormalities in the perception or expression of reality. "SNPs annotated to genes previously associated to obesity traits (LINGO2, NELL1) and neurological disorders (schizophrenia (ACSM1, KIF26B, NALCN)), and alcohol and nicotine dependence (LINGO, SH3BP5) were found among Prudent reported dietary pattern score associated-SNPs." (PMID 28644415, 2017).
abortion (1 paper, 2025). the ending of pregnancy by removing a fetus or embryo before it can survive outside the uterus. "MMP9 and DC-SIGN were associated with increased spontaneous abortion risk(OR=1.11(1.03-1.19), P=3.70x10-3; OR=1.09(1.02-1.16),p=9.89x10-3), while HBAZ and NELL1 hadprotective effects (OR=0.96(0.94- 0.99),p=5.20x10-3; OR=0.94(0.9-0.98),p=8.54x10-3)." (PMID 40674570, 2025).
breast carcinoma (1 paper, 2024). "It has been reported that NELL-1 was overexpressed at both transcriptional and protein levels in neuroblastoma and osteosarcoma, as well as prostate cancer, lung cancer and breast cancer." (PMID 38686366, 2024).
Coronal craniosynostosis (1 paper, 2013). Premature closure of the coronal suture of skull. "The secreted molecule NELL-1 (NEL-like protein 1) was first discovered to have osteoinductive properties by its overexpression during premature bone formation in human sporadic coronal craniosynostosis." (PMID 24416618, 2013).
Crohn disease (1 paper, 2007). A gastrointestinal disorder characterized by chronic inflammation involving all layers of the intestinal wall, noncaseating granulomas affecting the intestinal wall and regional lymph nodes, and transmural fibrosis. "In summary, we have successfully performed a systematic genome-wide association scan in Crohn disease that led to the identification of the NELL1 gene on chromosome 11p15.1 as a novel susceptibility gene for IBD." (PMID 17684544, 2007). "We have identified NELL1 as a novel disease gene for Crohn disease (CD), a result that was obtained in a genome-wide case-control association scan with 116,161 SNPs and by extensive replication in three independent samples from three distinct ethnicities." (PMID 17684544, 2007).
esophageal cancer (1 paper, 2024). A primary or metastatic malignant neoplasm involving the esophagus. "In addition to renal cancer, NELL-1 gene promoter methylation can also be detected in colorectal cancer, esophageal cancer." (PMID 38686366, 2024).
glomerulonephritis (1 paper, 2025). A renal disorder characterized by damage in the glomeruli. "Several podocyte antigens, such as PLA2R1, THSD7A, NELL1, HTRA1, and nephrin, are the primary targets of deleterious autoantibodies in glomerulonephritis patients." (PMID 40072092, 2025).
glomerulosclerosis (1 paper, 2024). A hardening of the kidney glomerulus caused by scarring of the blood vessels. "Exceptions included testican-2 and NELL1, which were associated with less glomerulosclerosis and IFTA, respectively, and higher eGFR; notably, both of these proteins demonstrated significantly higher levels from artery to renal vein, demonstrating net kidney release." (PMID 38656806, 2024).
leukemia (1 paper, 2023). A malignant (clonal) hematologic disorder, involving hematopoietic stem cells and characterized by the presence of primitive or atypical myeloid or lymphoid cells in the bone marrow and the blood. "In our series, the clinicopathological features of T-ALL and concurrent MN negative for THSD7A and NELL1, and segmentally and mildly positive for PLA2R indicated true paraneoplastic MN, although the exact pathogenetic link between the leukemia and MN remained unexplored." (PMID 37550626, 2023).
lung carcinoma (1 paper, 2021). "Interestingly, NELL1 overexpression is associated with chemotherapeutic sensitivity to cis/carboplatin and reduced colony formation in lung cancer, suggesting that epigenetic regulation of this gene may be important in chemotherapy response." (PMID 34922619, 2021).
lupus nephritis (1 paper, 2025). Glomerulonephritis in the context of systemic lupus erythematosus. "All lupus nephritis and secondary MGN cases were negative for NELL1, constituting 10.9% (24/219) of the primary MGN group." (PMID 39249508, 2025).
malignant bone tumors (1 paper, 2021). "Another marker correlated with osteochondral differentiation and cell proliferation is NEL-like protein 1 (NELL-1), expressed in benign and malignant bone tumors." (PMID 34069269, 2021).
multiple sclerosis (1 paper, 2024). A progressive autoimmune disorder affecting the central nervous system resulting in demyelination. "However, these genetic studies corroborate the discussed roles of NELL1 in bone and dental health, and raise questions about potential genetic predispositions in the small subset of patients with NELL1 MN in the setting of multiple sclerosis or IBD." (PMID 38596642, 2024).
osteoarthritis (1 paper, 2020). A noninflammatory degenerative joint disease occurring chiefly in older persons, characterized by degeneration of the articular cartilage, hypertrophy of bone at the margins and changes in the synovial membrane. "Lately, there was a publication reporting that neural EGFL like 1 (NELL-1)-haploinsufficient mice displayed increased inflammatory markers and symptoms of aggravated and accelerated osteoarthritis." (PMID 32372949, 2020).
prostate carcinoma (1 paper, 2024). A carcinoma that arises from epithelial cells of the prostate gland. "Similar to THSD7A, the association between NELL1 MN and malignancy is made further intriguing by the presence of tumor staining in reported cases, usually of solid tumors like breast or prostate cancer for NELL1." (PMID 38596642, 2024).
renal carcinoma (1 paper, 2024). A carcinoma arising from the epithelium of the renal parenchyma or the renal pelvis. "Studies on the pathogenic mechanism of NELL-1 in malignant tumors show that abnormal CpG islands and promoter methylation lead to downregulation of NELL-1 expression, thereby regulating the malignant behavior of renal cancer cells." (PMID 38686366, 2024). "However, NELL-1 was downregulated at the gene, transcript and protein levels in renal cancer, gastric cancer and lymphoma." (PMID 38686366, 2024).
rheumatoid arthritis (1 paper, 2025). A chronic, systemic autoimmune disorder characterized by inflammation in the synovial membranes and articular surfaces. "More recent reports have shown that NELL1-associated MGN is associated with lipoic acid use, traditional indigenous medicine (mercury) exposure, hematopoietic stem cell transplantation, and autoimmune diseases including rheumatoid arthritis (RA)." (PMID 39249508, 2025).
ulcerative colitis (1 paper, 2007). An inflammatory bowel disease involving the mucosal surface of the large intestine and rectum. "Further confirmation in a large German ulcerative colitis (UC) sample indicated that NELL1 is a ubiquitous IBD susceptibility locus (combined p<10−6; OR = 1.66, 95% CI: 1.30–2.11)." (PMID 17684544, 2007).
cancer (18 papers, 2015 to 2025). A tumor composed of atypical neoplastic, often pleomorphic cells that invade other tissues. "The association between NELL-1 (+) MN and malignancy remains controversial, with reported cancer rates varying widely." (PMID 40978725, 2025). "To date, more than a dozen MN-related antigens have been identified, of which THSD7A and NELL-1 are thought to be associated with malignancies." (PMID 38686366, 2024). "Recent advancements in the identification of MN-specific antigens, such as THSD7A and NELL-1, suggest a potential association with malignant tumors, yet definitive proof of this relationship remains elusive." (PMID 38686366, 2024). "While initially felt to represent a mainly primary type of MN, NELL1-associated MN has been found to be associated with malignancy in 11.7-35% of cases." (PMID 34899763, 2021). "For example, PLA2R-, THSD7A-, or NELL1-associated MN has been detected in malignancies." (PMID 41445719, 2025). "About 11.7% to 33% of MN with malignant tumors are associated with anti-NELL-1." (PMID 37685941, 2023). "NELL1 has been found to be associated with a variety of tumors, which may inhibit the progress of cancer." (PMID 35203526, 2022). "The combination of serum methylated TAC1, SEPT9, and NELL1 could also depict a higher cancer-specific death risk after CRC surgical resection (P = 0.001) than any single marker at 6 months but not after 1 year postsurgery." (PMID 30944663, 2019). "Although NELL-1 has been proven to play a role in tumorigenesis and development, its pathophysiological mechanism in malignant tumors remains to be further studied." (PMID 38686366, 2024). "Several previous studies have directly demonstrated a relationship between NELL1 and the proliferation and metastasis of cancer cells, particularly in RMS." (PMID 35447734, 2022). "When the prevalence of cancer was analyzed per subcategory of MN identified by antigen, NELL-1 came first (33%) followed by THSD7A (11%) while PLA2R-positive cases accounted for only 4%." (PMID 33562791, 2021). "Taken together, these finding suggest that NELL1 acts in different manners in diverse cancer types and that further investigation is warranted to clarify its function." (PMID 28380437, 2017). "Collectively, these findings indicate that NELL-1 could be an important biomarker for MN treatment decisions and cancer surveillance, warranting further study." (PMID 40978725, 2025). "NELL1 overexpression promoted tumor invasion, implying that NELL1 may function as an oncogene and play an important role in cancer progression." (PMID 35447734, 2022). "Serum methylated SST was significantly associated with cancer-specific survival among all other detected markers tested in the same study (TAC1, MAL, SEPT9, NELL1, CRABP1, EYA4, and CEA) at the preoperative time point, while its methylation status after operation had no value on prognosis." (PMID 30944663, 2019). "Conversely, a high frequency of NELL1 promoter hypermethylation was found in several solid tumors suggesting that NELL1 inactivation could be involved in cancer progression." (PMID 28380437, 2017). "Furthermore, immunohistochemical analyses revealed that Nell-1 staining was less intense in cancer tissue relative to normal tissue and that the tumor cells had spread to the muscle layer." (PMID 26090379, 2015). "Malignant tumors might be present in anti-NELL-1 positive MN." (PMID 37685941, 2023). "Targeting NELL1 could therefore prove useful in the fight against cancers." (PMID 35447734, 2022). "We also identified a novel mechanism in addition to DNA hypermethylation by which the tumor suppressors NELL1 and NELL2 were downregulated in cancer tissues." (PMID 34238763, 2021). "NELL1 and NELL2, which act as suppressors in various types of cancer including osteosarcoma, were identified as proteins that interact with ANO5." (PMID 34238763, 2021). "Both NELL1 and THSD7A have been shown to exhibit increased protein expression in certain human cancers." (PMID 34899763, 2021).
cancer (continued). "In previous studies, NELL1 and NELL2, which act as tumor suppressors, were downregulated in a variety of cancers including osteosarcoma." (PMID 34238763, 2021). "Furthermore, hypermethylation of NELL1 and NELL2, which decreased their transcription, was common in cancer." (PMID 34238763, 2021).
tumor (15 papers, 2015 to 2026). "Importantly, four of these patients achieved remission of MN after tumor resection and supportive therapy alone, suggesting a possible causal link between malignancy and NELL-1 (+) MN in selected cases." (PMID 40978725, 2025). "Additionally, demonstration of an association between NELL1 MN activity and/or anti-NELL1 antibodies with tumor regression would further support the association." (PMID 38596642, 2024). "Additionally, a recent study reported that 33% of NELL1-associated MN cases also had a tumor history, indicating a possible association between NELL1-associated MN and malignancies." (PMID 33825066, 2021). "This review aims to provide a comprehensive analysis of the molecular mechanisms of NELL-1 in osteogenesis, chondrogenesis, immune regulation, and tumor suppression." (PMID 42099386, 2026). "Genome-wide association study of NELL1, role of NELL1 in other physiologic and pathologic processes, and connection between NELL1 MN and malignancy with relevance of NELL1 tumor staining are examined." (PMID 38596642, 2024). "We have now extended this work to elucidate the role of CNTNAP4, a high-affinity receptor for NELL-1 in mediating tumor progression." (PMID 36599925, 2023). "However, it has been reported that THSD7A-positive MN and NELL-1-positive MN occur under the action of tumor, drugs and other secondary factors." (PMID 38250076, 2023). "Similarly, MAPK and FAK signaling pathways were significantly downregulated in CNTNAP4 KO cell clones, but to a lesser extent in NELL1 KO tumor cells." (PMID 36599925, 2023). "NELL1 expression is typically reduced in osteosarcoma compared with benign tumor tissues, indicating that it may act as a tumor suppressor." (PMID 34238763, 2021). "To investigate if there is any correlation between NELL1 expression and RMS patients’ outcome, we performed an association analysis with known RMS prognostic factors, such as histology, presence of translocations, tumor size and clinical stage." (PMID 28380437, 2017). "At the same time, high NELL1 expression levels identifies patients with higher risk of failure, while age and tumor size at diagnosis did not appear to be significantly associated with disease outcome." (PMID 28380437, 2017). "The expression of NELL1 was then assessed in an expanded cohort of RMS tumor specimens by qRT-PCR." (PMID 28380437, 2017). "Statistical analysis uncovered a correlation between NELL1 expression and established risk factors for RMS, such as alveolar histology and positive fusion status; patients with those characteristics have, in fact, high levels of NELL1 just as do patients with advanced tumor stages." (PMID 28380437, 2017). "The distinct isoforms of NELL-1, such as NELL-1570 and NELL-1-ΔE, exhibit specific functional properties and hold significant therapeutic promise, particularly in bone regeneration and tumor suppression." (PMID 42099386, 2026). "Inhibition of ANO5 increased NELL1 and NELL2 expression in vivo and decreased tumor proliferation." (PMID 34238763, 2021). "Moreover, a subcutaneous tumor transplantation model revealed that ANO5 knockdown reduced osteosarcoma cell proliferation and increased NELL1 and NELL2 expression in vivo." (PMID 34238763, 2021). "Furthermore, both NELL1 and NELL2 were increased in tumor tissues with lower ANO5 expression, while the expression of KI67 (a biomarker for proliferation) was decreased." (PMID 34238763, 2021). "This revealed that tumor cells in MBMs not only exhibited significantly upregulated tumorigenesis and maintenance genes (e.g., MET and TBX2), but also expressed neural differentiation markers (e.g., NRG3, NELL1, NCAM1, ADNP) and cell adhesion molecules (e.g., CDH1, PRKCA)." (PMID 41284647, 2025). "Therefore, it seems that in RMS tumor cells NELL1 is not affecting cell proliferation and apoptosis pathways but instead has a role in the invasive phenotype." (PMID 28380437, 2017).
tumor (continued). "The study also found that high NELL1 levels are correlated with negative RMS prognostic factors and with poor tumor outcomes." (PMID 28380437, 2017).